ALB (albumin)
Diseases named in the same sentence as ALB in open-access papers (continued):
Sharing a sentence is not in itself a finding about the gene and the disease.
pancreatitis (continued). "ROC analysis was used to calculate the appropriate sensitivity, specificity, positive predictive value, negative predictive value, positive likelihood ratio, negative likelihood ratio and diagnostic accuracy of CRP/Albumin ratio in determining severe pancreatitis against a CT severity score." (PMID 36268355, 2022). "In the comparison of clinical data and complications in patients with pancreatitis, fasting days, BISAP score, patient’s first bowel movement time, NLR, Glu, CRP, ALB, and BUN all have an impact on the occurrence of complications in patients with pancreatitis." (PMID 39331915, 2024). "Dogs with pyometra and pancreatitis showed statistically significantly higher serum CRP and Hp and lower serum PON-1 and albumin concentrations when compared with healthy dogs." (PMID 37344860, 2023). "One woman also developed pancreatitis and OHSS three weeks after embryo transfer and was successfully treated with intravenous fluids, methylprednisolone, heparin and albumin." (PMID 36396849, 2022). "Lastly, Delong's was applied for statistical comparisons between CRP/albumin ratio and CRP along as predictive marker of severity of pancreatitis." (PMID 36268355, 2022). "Although, the statistical difference between CRP/albumin ratio and CRP levels alone isn't much, but overall, the sensitivity and accuracy are increased to predict severe pancreatitis by bringing albumin into the picture." (PMID 36268355, 2022). "The study found that aggressive intravenous hydration with lactated Ringer’s solution and 20% human albumin did not significantly reduce post-ERCP pancreatitis (6.7% vs. 6.3%, p = 0.873)." (PMID 40218161, 2025). "Aggressive peri-ERCP intravenous hydration with lactated Ringer's solution combined with 50 ml of 20% human albumin did not prevent post-ERCP pancreatitis." (PMID 39836543, 2024). "The CRP/albumin ratio integrates two laboratory parameters that reflect the inflammatory response and negative protein balance in pancreatitis." (PMID 38283464, 2023). "In the first one, the values of CRP and ferritin, together with the other three APPs that are include in our profiles (i.e., Hp, albumin and PON-1) in dogs with pyometra were compared with healthy dogs and with dogs suffering from another inflammatory condition such as pancreatitis." (PMID 37344860, 2023). "Blood samples from patients with AP, normal controls, and rodents with pancreatitis or those administered different nonesterified fatty acids (NEFAs) were analyzed for albumin-unbound NEFAs, microbiome, and inflammatory cell injury." (PMID 37263302, 2023). "CRP/albumin ratio has higher sensitivity and negative predictive value to predict severe pancreatitis than CRP alone and hence give additional advantage as a prognostic marker, although Delong's test to compare AUROC was indifferent (P-value: 0.22)." (PMID 36268355, 2022).
metastatic disease (38 papers, 2006 to 2025). "In our study, there was a trend for increased readmission risk in patients with metastatic disease (p = 0.155) and albumin levels (p = 0.055)." (PMID 40283507, 2025). "For instance, metastatic disease and albumin levels were identified as significant predisposing factors for readmissions in other studies." (PMID 40283507, 2025). "Factors related to unplanned hospitalizations were ECOG PS 2, IADL ≤ 7, ADL ≤ 5, Charlson Comorbidity Score ≥ 2, creatinine clearance ≤ 50 mL/min, albumin ≤ 35 g/dL, weight loss ≥ 5% and metastatic disease." (PMID 35008291, 2021). "Risk factors for early death were ADL ≤ 5, Charlson Comorbidity Score ≥ 2, weight loss ≥ 5%, metastatic disease, serum albumin levels ≤ 35 g/dL, and hemoglobin levels < 11 g/dL." (PMID 35008291, 2021). "In triple-negative breast cancer, a novel peptide–drug conjugate exploits enhanced albumin metabolism in PTEN-deficient cells to deliver chemotherapeutic payloads, showing promise against metastatic disease." (PMID 40647429, 2025). "At the time of HCC diagnosis, univariate regression analysis identified tumor growth pattern, extrahepatic metastatic disease, therapy, Albumin-Bilirubin (ALBI) grade, alpha-fetoprotein (AFP), and BMD as prognostic factors for median OS." (PMID 40845067, 2025). "A positive association of PhA with nutritional status, BMI, fat-free mass, and serum albumin and transferrin levels has been shown in studies involving cancer patients with advanced disease (metastatic disease)." (PMID 39205363, 2024). "Further, the patients already had characteristics of worse prognosis, such as lower hemoglobin and albumin levels, and metastatic disease, which made it difficult to identify factors for early mortality." (PMID 37092495, 2023). "In the present study, among 4 patient parameters (metastatic disease, serum albumin, blood urea nitrogen and NLR), NLR showed the most significant difference in overall survival between two groups." (PMID 35413824, 2022). "We also revealed some predictive factors besides lower BED10 for shorter overall survival including presence of metastatic disease, lower serum albumin concentration, higher blood urea nitrogen level and higher neutrophil-to-lymphocyte ratio." (PMID 35413824, 2022). "Cluster B was associated with the frailest patients with metastatic disease, mainly driven by a high CRP level at baseline, and low albumin during the study follow-up." (PMID 34830936, 2021). "The other factors included in the multivariable analyses for overall survival were platinum sensitivity (adjusted HR 0·71, 0·49–1·00; p=0·050), high albumin at baseline (0·54, 0·37–0·78; p=0·0010), and metastatic disease (1·33, 0·85–2·09; p=0·21)." (PMID 33798493, 2021). "Furthermore, it has been illustrated that a PD-1 inhibitor combined with albumin-bound paclitaxel is effective in metastatic tumors such as upper tract urothelial carcinoma and hypopharyngeal/laryngeal squamous cell carcinoma." (PMID 40919161, 2025). "Similarly, age- and storage-adjusted serum albumin declined significantly in women with localized disease and in women with metastatic disease." (PMID 32723677, 2020). "However, it is noteworthy that in the women with early stage disease, serum levels of age- and storage- adjusted calcium and age- and storage-adjusted albumin showed significant changes post-diagnosis, similar to those of women with metastatic disease." (PMID 32723677, 2020). "In mice, albumin/AlbiVax nanocomplexes dramatically enhanced the potency and durability of T cell responses, and significantly inhibited tumor progression or eradicated tumors in multiple primary or metastatic tumors." (PMID 29203865, 2017). "Metastatic disease, ECOG performance status, and albumin level were significantly related to hospitalization." (PMID 40283507, 2025).
metastatic disease (continued). "Advanced stage, higher T stage, nodal involvement, metastatic disease, poor ECOG PS at diagnosis, low serum albumin, and presence of PNI, were significant predictors for death." (PMID 37232803, 2023). "On univariate analysis poor performance status, low serum albumin, presence of PNI, higher T stage, nodal involvement, metastatic disease, and advanced stage were significant predictors for death." (PMID 37232803, 2023). "In multivariate analysis, metastatic disease (OR: 2.52 95% CI 1.48–4.29 p = 0.001), Eastern Cooperative Oncology Group (ECOG) performance status (OR: 1.58 95% CI 1.04–2.42 p = 0.034), and lower albumin levels (OR: 0.42 95% CI 0.29–0.61 < 0.001) were significantly related to hospitalization." (PMID 40283507, 2025). "High albumin correlates with improved DCR (71.9% versus 25%, p = 0.01), and metastatic disease involving non-liver sites was associated with high ORR (25% versus 3.6%, p = 0.04)." (PMID 38339307, 2024). "In multivariate analysis, absence of metastatic disease, higher biological effective dose, higher serum albumin level, lower blood urea nitrogen level and lower neutrophil-to-lymphocyte ratio (NLR) were associated with longer overall survival." (PMID 35413824, 2022). "Multivariate analysis showed that absence of metastatic disease, higher biological effective dose, higher serum albumin level, lower blood urea nitrogen level and lower neutrophil-to-lymphocyte ratio (NLR) were associated with longer overall survival." (PMID 35413824, 2022). "In all, 72 (75%) patients had not received cytotoxic chemotherapy for metastatic disease prior to the measurement of C-reactive protein and albumin concentrations." (PMID 16404432, 2006). "In multivariate analysis, metastatic disease (OR: 2.52 95% CI 1.48–4.29 p = 0.001), Eastern Cooperative Oncology Group (ECOG) performance status (OR: 1.58 95% CI 1.04–2.42 p = 0.034), and a decrease in albumin levels (OR: 0.42 95% CI 0.29–0.61 < 0.001) were significantly related to hospitalization." (PMID 40283507, 2025). "Whether low albumin per se is a negative prognostic factor as an expression of high tumor burden or liver dysfunction due to metastatic disease, or as a surrogate parameter for cachexia is beyond the scope of this study." (PMID 39414641, 2024).
viral infection (38 papers, 2010 to 2025). "Another potential mechanism for the low serum albumin levels observed in this cohort is the inflammatory process associated with viral infections, specifically neurogenic inflammation." (PMID 31314114, 2019). "On the other hand, age at the time of KT and donor CMV serostatus showed a significant higher association with the incidence of viral infections, while a higher eGFR and serum albumin levels also showed an association with decreased viral infection incidence rates within 12 months after KT." (PMID 33919913, 2021). "Moreover, over half of the admissions were due to events unrelated to the albumin infusion program, such as viral infections and/or morbidity associated with the primary kidney disease." (PMID 33520897, 2020). "Compared to TPE using FFP, TPE using an albumin solution has the advantage of having a lower risk of causing allergic reactions and unknown virus infections, in addition to its lower medical costs; therefore, an albumin solution is recommended as a replacement fluid for TPE generally." (PMID 38672203, 2024). "However, an increase in the CSF/blood-albumin-ratio might also be caused by changes in the CSF production and resorption or viral infection of the choroid plexus." (PMID 36340780, 2022). "Concentrations of 68 metabolites were significantly higher in viral infections than in autoimmune neuroinflammation, and the 10 most accurate metabolite biomarkers (AUC = 0.89–0.93) were substantially better than Q-albumin (AUC = 0.86)." (PMID 37919735, 2023). "To assess lung damage following viral infection, albumin levels in the BAL were assessed and we found that senolytic treatment was unable to significantly improve lung pathology and/or the return to homeostasis in this context." (PMID 37396956, 2023). "In critically ill patients such as those poisoned by insecticides or suffering from bacterial or viral infections, eventually albumin replacement strategies must be individually established to maintain normal blood volume, if possible, by first measuring it." (PMID 37047631, 2023). "Serum albumin levels are used as a predictor in determining the severity of acute viral infections and have a high significance in relation to the survival of critically ill patients." (PMID 36552520, 2022). "We report blood–brain barrier disruption, likely related to high cytokine levels and endothelial viral infection, with extravasation of fluid, Gadolinium-based contrast material and albumin into the extracellular space." (PMID 34001896, 2021). "Albumin is an indicator that reflects nutritional status, and decreased albumin levels indicates the body has lower levels of resistance to viral infection." (PMID 33243228, 2020). "Based on our results it is conceivable that the generated HOCl reacts with bovine serum albumin, which is usually present in high concentrations in cell culture media, and therefore mBSA would be present during viral infection." (PMID 20525179, 2010). "In addition to inflammation, nutritional support, liver function, cardiovascular disease, viral infections, renal disease, neoplasms, and auto-rheumatic immune disorders can potentially lower albumin levels." (PMID 38779217, 2024). "Of the standard CSF parameters, the best biomarkers were: CSF cell count for viral infections vs. controls (area under the ROC curve, AUC = 0.93), Q-albumin for viral infections vs. autoimmune neuroinflammation (AUC = 0.86), and IgG index for autoimmune neuroinflammation vs. controls (AUC = 0.90)." (PMID 37919735, 2023). "This is based on the observation that albumin accounts for the majority of total serum protein, while with viral infections, plasma cell malignancies, or autoimmune conditions there is an excess of immunoglobulins, raising the total amount of serum protein independent of albumin." (PMID 26629820, 2015).
viral infection (continued). "The patients with viral infection were younger, had a lower body mass index (BMI), a lower platelet count, higher level of albumin, better ALBI score, and better mALBI grade than those with non‐viral infection." (PMID 36226511, 2023). "Consistent with the binding data, neither CD147-QMP nor human albumin was able to suppress viral infection." (PMID 38077689, 2023). "Albumin is found in the HUI model, SHASTA index, and NAFLD fibrosis score—only the last of the markers has been verified for usage in NAFLD patients (the other two are suited for hepatotropic viral infections)." (PMID 38137829, 2023). "In addition, no intergroup differences were noted in terms of the classification of serum ALT, ALB, TB, PT, and AFP levels; Child-Pugh score; status of viral infection; and BCLC stage." (PMID 32280472, 2020). "Among host proteins directly interacting with virus proteins, the strongest connection with the ACE2 network occurs by ALB (30 interactors form ACE2 network) and CAV1 (13 interactors) which had affected the co-expression network after virus infection in hiPSC-CMs." (PMID 33233425, 2020). "When serum albumin was treated with HOCl at higher concentrations, as described in the literature (10 mg/ml), we observed no inhibitory activity in our viral infection and syncytium assays (data not shown)." (PMID 20525179, 2010). "NiV-infected animals generally had higher C-reactive protein (CRP) and lower albumin levels (corresponding to positive and negative acute phase proteins, respectively), indicating the body’s response to active viral infection, and also high blood urea concentrations, suggesting renal dysfunction." (PMID 39870114, 2025). "The cells grew in the presence of albumin, but no protection was observed after virus infection." (PMID 32244308, 2020).
AIDS (37 papers, 2004 to 2026). A syndrome resulting from the acquired deficiency of cellular immunity caused by the human immunodeficiency virus (HIV). "Findings from the Strategic Timing of Antiretroviral Treatment (START) study demonstrated that in healthy adults with early stage HIV infection, serum albumin predicted future non-acquired immune deficiency syndrome (AIDS)-related events." (PMID 30515432, 2018). "Other studies have also found that serum albumin has remained associated with serious non-AIDS events and CVD mortality after adjusting for markers of systemic inflammation both in the HIV-infected population and in uninfected older men, respectively." (PMID 30515432, 2018). "The allergic history, opportunistic infection, viral load, CD4 cell count, high globulin and low albumin were the risk factors correlated with death in HIV/AIDS patients with drug eruption." (PMID 27796328, 2016). "Our finding that AA was inversely associated with CRP and triglycerides and positively associated with HDL-C, CD4+ cell count and plasma albumin suggests that individual fatty acids may influence clinical outcomes in HIV/AIDS patients." (PMID 26161268, 2015). "Several studies have shown that CD4+ T cell count and albumin levels are the two main markers that can be considered the first indices to look at in terms of AIDS progression." (PMID 37736888, 2023). "The study assessed the effect of some highly active antiretroviral therapies (HAART), used in the management of HIV/AIDS in Cameroon, on oxidative stress markers such as malondialdehyde (as TBARs), albumin, protein carbonyl content and protein sulfhydryls groups." (PMID 16859567, 2006). "Studies have shown that the serum albumin concentration is a predictor of the progression of HIV-related advanced disease and AIDS-related mortality." (PMID 40898300, 2025). "The objective of this article was to report on the nutritional outcomes using albumin and body mass index outcomes as a subset of a larger study among adults living with HIV and/or AIDS." (PMID 29943613, 2018). "Mortality in the early ART treatment period is higher among patients with low BMI, low CD4+ T-cell counts, low hemoglobin, low serum albumin and phosphate levels, advanced HIV/AIDS stage, and immune reconstitution inflammatory syndrome." (PMID 26161268, 2015). "Furthermore, studies reported that serum albumin is a useful prognostic marker for HIV/AIDS care and independent predictor marker of non-AIDS morbidity in PLWH, such as cardiovascular diseases." (PMID 40898300, 2025). "Compared with the survivors, non-survivors with AIDS-PCP exhibited a lower albumin and higher D-dimer, CRP, LDH and Kyn/Trp ratio." (PMID 30832615, 2019). "In these 4576 healthy adults with early stage HIV infection, serum albumin predicted future non-AIDS-related events (mainly non-AIDS cancer and CVD events) and hospitalizations." (PMID 30515432, 2018). "Low basal albumin levels were independently related to in-hospital mortality, and fever at admission was related to better prognosis in HIV-infected patients with disseminated TB and AIDS." (PMID 20811589, 2011). "A study found that for every 2.5 mg/L decrease in the serum albumin concentration, there is a corresponding 16% and 39% increase in the likelihood of an extended hospital stay and an increased chance of mortality, respectively, in critically ill inpatients, including patients with HIV/AIDS." (PMID 40898300, 2025).